NUBPL (NUBP iron-sulfur cluster assembly factor, mitochondrial)
Description:
Iron-sulfur cluster transfer protein involved in the assembly of the mitochondrial membrane respiratory chain NADH dehydrogenase (Complex I). May deliver one or more Fe-S clusters to complex I subunits.
Synonyms: C14orf127; FLJ12660; IND1; huInd1; MC1DN21
Tractability: Antibody: its Gene Ontology location is reachable by antibodies, with high confidence. PROTAC: its protein half-life has been measured.
Safety:
Unwanted effects reported when the protein is acted on. In parentheses: how it was acted on, where the effect was seen, and who reports it.
adverse cardiovascular events (source: ClinPGx)
Gene: Protein-coding gene on chromosome 14 (31,489,956 to 31,861,226, forward strand). Ensembl gene ENSG00000151413.
Subcellular location: Mitochondrion
Subcellular location (Human Protein Atlas): Mitochondria
Pathways (Reactome):
Metabolism: Complex I biogenesis
Gene Ontology:
Molecular function: 4 iron, 4 sulfur cluster binding; protein binding; ATP binding; ATP-dependent FeS chaperone activity; iron-sulfur cluster binding
Biological process: mitochondrial respiratory chain complex I assembly; mitochondrion organization; iron-sulfur cluster assembly
Cellular component: mitochondrion; mitochondrial matrix
Genetic constraint (gnomAD): Loss-of-function variants: 18 observed, 29.78 expected, observed/expected ratio (o/e) 0.6, 90% interval 0.42 to 0.9. The upper end of that interval is the gene's LOEUF score, 0.9, which puts it in group 3 of 6, group 1 being the genes least tolerant of losing a copy. Missense variants: 319 observed, 299.67 expected, observed/expected ratio (o/e) 1.06, 90% interval 0.97 to 1.17. Synonymous variants: 111 observed, 101.03 expected, observed/expected ratio (o/e) 1.1, 90% interval 0.94 to 1.29.
Gene-disease validity (ClinGen):
ClinGen rates the evidence that NUBPL causes each of these diseases.
mitochondrial disease (autosomal recessive): Definitive.
Leigh syndrome (autosomal recessive): Moderate. A progressive neurological disease defined by specific neuropathological features associating brainstem and basal ganglia lesions.
Homologues: Orthologues: chimpanzee NUBPL (99% identical), macaque NUBPL (97% identical), dog NUBPL (89% identical), guinea pig NUBPL (88% identical), mouse Nubpl (88% identical), rat Nubpl (88% identical), rabbit NUBPL (88% identical), pig NUBPL (81% identical), zebrafish nubpl (69% identical), tropical clawed frog nubpl (68% identical), Drosophila melanogaster Nubpl (39% identical). Paralogues in human: NUBP1 (38% identical), NUBP2 (30% identical).
Diseases named in the same sentence as NUBPL in open-access papers:
NUBPL is named in the same sentence as 42 diseases in open-access papers, as found by Europe PMC text mining. Sharing a sentence is not in itself a finding about the gene and the disease. The quoted sentences say what the papers report.
Parkinson disease (6 papers, 2018 to 2025). A progressive degenerative disorder of the central nervous system characterized by loss of dopamine producing neurons in the substantia nigra and the presence of Lewy bodies in the substantia nigra and locus coeruleus. "Meanwhile, Cluster 25 exhibited relatively lower RBS-R scores than those of the other clusters but higher DCDQ and SCQ scores, with HIVEP3 and NUBPL being associated with Parkinson’s disease." (PMID 40440618, 2025). "In an unbiased genome-wide screen for copy number variants (CNVs) on a cohort of Parkinson's disease (PD) patients, we identified in one patient a complex chromosomal rearrangement involving the nucleotide binding protein-like (NUBPL) gene on chromosome 14q12." (PMID 33224084, 2020). "NUBPL encodes nucleotide binding protein-like on chromosome 14q12, and functional variants in the gene are associated with mitochondrial complex I deficiency and linked to leukoencephalopathy and Parkinson’s disease." (PMID 36167494, 2022). "Furthermore, variants in NUBPL were hypothesized as risk factors for Parkinson’s disease." (PMID 34944310, 2021). "G138D is predicted to be damaging to NUBPL and has been found in two Parkinson’s disease patients (P. Eis and E. Hatchwell, personal communication)." (PMID 29982452, 2018).
colorectal cancer (5 papers, 2021 to 2025). A primary or metastatic malignant neoplasm that affects the colon or rectum. "Previous research has demonstrated that colorectal cancer cells express NUBPL at a high level, and that elevated NUBPL levels can promote metastasis and epithelial-mesenchymal transition (EMT)." (PMID 40539058, 2025). "Overexpression of NUBPL enhanced migration and invasion in colorectal cancer cells, while silencing suppressed these malignant traits." (PMID 41157129, 2025). "Data suggest that NUBPL promotes the migration and invasion of colorectal cancer cells by inducing EMT and activating ERK." (PMID 39896807, 2024). "While low FOXRED1 expression correlates with poor prognosis in colorectal cancer, NUBPL KD decreases cell invasion." (PMID 38898058, 2024). "NUBPL is a protein that helps put together the main respiratory chain component of mitochondria, human mitochondrial complex I. Compared to normal tissue, colorectal cancer (CRC) exhibits much higher NUBPL expression, which is highly correlated with lymph node metastases and advanced stages." (PMID 40539058, 2025). "In addition to its central role for the mitochondrial respiratory chain, overexpression of NUBPL has been documented in melanoma and colorectal cancer tissue." (PMID 34696794, 2021).
Ataxia (2 papers, 2019 to 2022). Ataxia refers to impaired coordination of voluntary muscle movement. "Patients affected by complex I deficiency harboring homozygous NUBPL variants typically have neurological problems including seizures, intellectual disability, and ataxia associated with cerebellar hypoplasia." (PMID 36280881, 2022). "Using whole exome sequencing, linkage analysis and homozygosity mapping, NUBPL mutations are now identified as the cause of autosomal recessive dystonia combined with cerebellar ataxia and pyramidal involvement in a UK kindred." (PMID 30897263, 2019). "Autosomal recessive NUBPL mutations were identified as the cause of early onset, generalized dystonia with cerebellar ataxia, pyramidal signs, preserved cognition and a distinctive MRI appearance with bilateral striatal necrosis (BSN) and cerebellar atrophy." (PMID 30897263, 2019). "NUBPL mutations cause early onset, autosomal recessive generalized dystonia with cerebellar ataxia, pyramidal signs, preserved cognition and a distinct magnetic resonance imaging appearance with BSN and cerebellar atrophy." (PMID 30897263, 2019).
bladder cancer (2 papers, 2025). "Further studies have implicated NUBPL dysregulation in gastric cancer and bladder cancer, with high NUBPL expression predicting poor prognosis and reduced responsiveness to immune checkpoint inhibitors." (PMID 41157129, 2025). "There is a study showing that in bladder cancer, high expression of NUBPL leads to a poor response to immune checkpoint inhibitors (ICI)." (PMID 40539058, 2025).
breast carcinoma (2 papers, 2023 to 2025). "For example, multiple Complex I subunits, such as NDUFB1, NDUFS4, NUBPL, and NDUFA7, have been implicated in the metabolic plasticity of breast cancer cells." (PMID 41157129, 2025).
gastric cancer (2 papers, 2025). A primary or metastatic malignant neoplasm involving the stomach. "We have confirmed that NUBPL is upregulated in gastric cancer and is associated with poor prognosis, while also influencing immune infiltration and treatment of gastric cancer cells." (PMID 40539058, 2025). "We examined the relationship between NUBPL expression and immune therapy results to ascertain if NUBPL expression influences the immune therapy response in patients with gastric cancer." (PMID 40539058, 2025). "The accuracy of the prognostic model derived from public databases requires further experimental validation, such as constructing immunohistochemical chips for gastric cancer to further analyze the prognostic value of NUBPL in gastric cancer." (PMID 40539058, 2025). "NUBPL was identified as a potential biomarker for prognosis and immunotherapy in gastric cancer patients through bioinformatics analysis in the study." (PMID 40539058, 2025). "Utilizing machine learning methods such as LASSO, Random Forest (RF), Boruta, SVM-RFE, and XGBoost, the disulfidptosis-related gene NUBPL was determined as a potential predictor for gastric cancer." (PMID 40539058, 2025). "To evaluate the impact of NUBPL on gastric cancer cells, we employed PI staining to quantify cell mortality and discovered that NUBPL overexpression markedly diminished cell death during glucose deprivation." (PMID 40539058, 2025). "Transwell assays have shown that NUBPL notably drives the aggression and dispersal of stomach cancer cells." (PMID 40539058, 2025). "We found that the aberrant expression of NUBPL markedly influences the metabolic pathways and immune microenvironment of gastric cancer, especially its impact on immune cell infiltration." (PMID 40539058, 2025). "In order to address this lacuna, we conducted an analysis of data from numerous databases to determine the potential impact of NUBPL on gastric cancer." (PMID 40539058, 2025). "PPI network was constructed, and the GO database as well as the KEGG database were employed to analyze the protein interactions and pathway enrichment of NUBPL in gastric cancer." (PMID 40539058, 2025). "In patients with elevated NUBPL expression levels, a reduced number of CD8-positive T cells is associated with adverse prognosis and gastric cancer progression." (PMID 40539058, 2025). "The aberrant expression of NUBPL significantly impacts the prognosis of gastric cancer and modulates metabolic and immune-related pathways." (PMID 40539058, 2025). "We also determined how NUBPL regulates disulfidptosis in gastric cancer and evaluated its effects on malignant phenotype in gastric cancer." (PMID 40539058, 2025). "The role of NUBPL in gastric cancer and its inhibition of disulfidptosis were validated using molecular biological methods." (PMID 40539058, 2025). "To detect the effect of NUBPL on the malignant phenotype of gastric cancer, we overexpressed NUBPL in GC cell lines AGS and MKN-45, and confirmed the overexpression efficiency through Western blotting." (PMID 40539058, 2025). "Therefore, NUBPL can serve as a key biomarker for gastric cancer, providing a new potential target for targeted therapy and immunotherapy." (PMID 40539058, 2025). "We also found that NUBPL inhibits disulfidptosis in gastric cancer cells." (PMID 40539058, 2025). "Abnormal NUBPL expression may facilitate gastric cancer progression and hence influence patient prognosis." (PMID 40539058, 2025). "The function of NUBPL in gastric carcinoma has been the subject of limited prior research." (PMID 40539058, 2025). "Our analysis indicates that NUBPL may be a viable target for gastric cancer treatment." (PMID 40539058, 2025). "We found evidence that NUBPL could be a good target for treating stomach cancer." (PMID 40539058, 2025). "However, our understanding of NUBPL’s exact function in gastric cancer is still limited." (PMID 40539058, 2025).
gastric cancer (continued). "In vitro experiments have shown that NUBPL affects the invasion and migration of gastric cancer cells, rather than proliferation and apoptosis, by regulating the PPP pathway and inhibiting disulfidptosis." (PMID 40539058, 2025). "In vitro, NUBPL affects the invasion and migration of gastric cancer cells, but not proliferation and apoptosis." (PMID 40539058, 2025). "Additionally, we found that NUBPL did not influence apoptosis in gastric cancer cells." (PMID 40539058, 2025).
diabetes (1 paper, 2017). "Up-regulation in diabetes compared to healthy and down-regulation following treatment in diabetes was observed for 5 genes: NUDT4, GSMT5, predicted NUBPL, predicted RGD1306157 and LOC362480." (PMID 28727746, 2017).
glioma (1 paper, 2025). A benign or malignant brain and spinal cord tumor that arises from glial cells (astrocytes, oligodendrocytes, ependymal cells). "GYS1, NDUFA11, OXSM, RPN1, and SLC3A2 play a role in promoting cancer in glioma, while LRPPRC, NCKAP1, NDUFS1, NUBPL and SLC7A11 play a role in inhibiting tumour." (PMID 39993959, 2025).
heart failure (1 paper, 2025). Inability of the heart to pump blood at an adequate rate to meet tissue metabolic requirements. "Dysfunction of NUBPL may exacerbate energy deficits and oxidative stress, consistent with its role in heart failure and ischaemic cardiomyopathy progression." (PMID 40070032, 2025).
melanoma (1 paper, 2021). A malignant, usually aggressive tumor composed of atypical, neoplastic melanocytes. "The antagonistic pathogenesis of vitiligo in relation to cancer specific enhanced cell motility and/or metastasis on typical melanoma predilection sites underlines a plausible involvement of RCBTB1, LITAFD, NUBPL, and PTP4A1." (PMID 34696794, 2021).
Mitochondrial encephalopathy (1 paper, 2013). "A branch-site mutation in the human gene encoding assembly factor NUBPL has recently been associated with mitochondrial encephalopathy and complex I deficiency in seven independent cases." (PMID 23828044, 2013).
otitis media (1 paper, 2022). Inflammation of the anatomical structures of the middle ear, which is most often caused by an infectious process. "Additional to replicating variants from the 23andMe study, we identified several novel variants within NUBPL gene region associated with otitis media." (PMID 36167494, 2022). "Two variants in nucleotide binding protein like (NUBPL) gene, the G allele of rs113235453 (OR, 1.50; 95% CI [1.30–1.73]; p = 3.04 × 10–8) and the A allele of rs74633202 (OR, 1.50; 95% CI [1.30–1.73]; p = 3.05 × 10–8) were associated with increased risk of otitis media." (PMID 36167494, 2022).
primary Sjogren syndrome (1 paper, 2023). "NUBPL is involved in the assembly of mitochondrial Complex I, and its expression in salivary glands is reported to be associated gamma delta T cell infiltration in primary Sjogren syndrome." (PMID 38068972, 2023).
Sepsis (1 paper, 2024). Sepsis is defined as life-threatening organ dysfunction caused by a dysregulated host response to infection. "The six intersection disulfidptosis‐related genes including LRPPRC, SLC7A11, GLUT, MYH9, NUBPL and GYS1 exhibited higher predictive ability for sepsis with an accuracy of 99.7%." (PMID 39400961, 2024).
vitiligo (1 paper, 2021). Generalized well circumscribed patches of leukoderma that are generally distributed over symmetric body locations and is due to autoimmune destruction of melanocytes. "In total, we propose the genes NUBPL, PHF11, SETDB2, RCBTB1, PTP4A1, and at a weaker replication level the genes LITAFD, CARHSP1 and OR2C1 as possible candidates for vitiligo-like depigmentation in grey horses." (PMID 34696794, 2021).
tumor (10 papers, 2021 to 2025). "NUBPL, on the other hand, may be associated with the metabolic state, proliferation, or survival of tumor cells." (PMID 39896807, 2024). "In patients with enhanced NUBPL expression, low CD8 T cell numbers were linked to worse prognosis and accelerated tumor development." (PMID 40539058, 2025). "Finally, since there is limited research on the NUBPL gene, we can also analyze its role from a pan-cancer perspective to provide a theoretical basis for NUBPL as a potential tumor marker." (PMID 40539058, 2025). "NUBPL was positively correlated with tumor purity, neutrophils." (PMID 39896807, 2024). "All the genes were highly expressed in tumor samples and except for the genes NDUFS1 and NUBPL, other genes showed apparent differences between the two groups." (PMID 38531953, 2024). "The results demonstrated that all 27 disulfrgs, except for NDUFS1, NUBPL, MYH10, and IQGAP1 genes, exhibited significantly higher expression in tumor tissues." (PMID 38831301, 2024). "We analyzed the expression of genes in tumor and normal samples, and the results showed that NDUFS1, NDUFS2, NDUFC1, and EPAS1 were downregulated in CRC, and SLC7A11, OXSM, LRPPRC, NDIFA11, NUBPL, and CONT1 were upregulated in CRC." (PMID 37978247, 2023). "The authors found that NUBPL induces epithelial–mesenchymal transition through the activation of ERK signaling pathway, a pathway which promotes tumor metastasis." (PMID 34696794, 2021). "The highlighted genes PHF11, SETDB2, CARHSP1 and LITAFD, are associated with the innate immune system, while the genes RCBTB1, LITAFD, NUBPL, PTP4A1, play a role in tumor suppression and metastasis." (PMID 34696794, 2021). "Moreover, using the TIMER database, we found that the expression of NUBPL and ACTB was closely related to tumor purity, while the correlation of SLC3A2 and DSTN with tumor purity was less pronounced." (PMID 39896807, 2024).
cancer (8 papers, 2021 to 2025). A tumor composed of atypical neoplastic, often pleomorphic cells that invade other tissues. "Meanwhile, the ESTIMATE algorithm was used for immune infiltration analysis and prediction of immunotherapy response, and the Genomics of Drug Sensitivity in Cancer (GDSC) database was utilized for the drug sensitivity analysis of NUBPL." (PMID 40539058, 2025). "A heatmap illustrated the correlation between NUBPL expression and 41 chemokines across pan-cancer data." (PMID 40539058, 2025). "We found that the expression of GYS1 and SLC7A11 were upregulated, while those of NCKAP1, NDUFS1, NUBPL, OXSM, RPN1, and SLC3A2 were downregulated in ccRCC tissues compared with those in the para-carcinoma tissues." (PMID 38271056, 2024). "Notably, RPN1, NUBPL, and OXSM demonstrate widespread CNV across various cancers." (PMID 38397869, 2024).
mitochondrial disease (5 papers, 2013 to 2025). "Since NUBPL was associated with mitochondrial disease resulting from complex I deficiency, the gene is routinely included in the list of candidate genes for genetic diagnoses." (PMID 29982452, 2018). "Infection is a common cause of morbidity in children with mitochondrial diseases; however, it is unclear if variation in NUBPL could influence the risk of infection through its role in mitochondrial complex I deficiency." (PMID 36167494, 2022). "Furthermore, we observed signals in important genes associated with ASD pathways, such as RGS3 in Cluster 24, encoding a regulator of G protein signaling; NUBPL in Cluster 25, previously associated with mitochondrial disease; and OR13F1 in Cluster 8, encoding an olfactory receptor." (PMID 40440618, 2025).
neurological disorders (2 papers, 2020 to 2025). "Given the extensive evidence for mitochondrial dysfunction — particularly reduced CI activity — in late-onset neurological disorders, we believe this novel finding provides a basis for the nomination of NUBPL as a gene that may cause or contribute to PD pathology." (PMID 33224084, 2020). "The majority of NUBPL research has concentrated on neurological disorders, with only a small number of studies investigating malignancies." (PMID 40539058, 2025).
NUBPL also shares sentences with these, for which no sentence is quoted: infection (3 papers); Alzheimer disease (1); cerebellar ataxia (1); Cerebellar atrophy (1); cholangiocarcinoma (1); clear cell renal adenocarcinoma (1); Cognitive impairment (1); Dystonia (1); encephalopathies (1); generalized dystonia (1); genetic disorder (1); Intellectual disability (1); ischaemic cardiomyopathy (1); leukodystrophy (1); Leukoencephalopathy (1); liver cancer (1); lung carcinoma (1); myopathy (1); prostate carcinoma (1); renal disease (1); skin cancer (1); spastic ataxia (1); stomach cancer (1).